CRP (C-reactive protein)
Diseases named in the same sentence as CRP in open-access papers (continued):
Sharing a sentence is not in itself a finding about the gene and the disease.
cancer (continued). "Although many studies involve palliative cancer patients, to our knowledge no other study has specifically studied CRP and s-alb values in patients during their last 2 months of life." (PMID 29534089, 2018). "Other promising markers (PKM2, CYFRA21.1 and MUC5AC) gave respectable classification performances in discriminating cancer cases from relevant benign controls and were independent of CRP and tumour site." (PMID 29707118, 2018). "Exercise did not appear to have a substantial effect on CRP among those cancer survivors with above normal baseline levels of CRP." (PMID 29789774, 2018). "Peripheral blood-derived inflammation-based markers, including C-reactive protein (CRP), neutrophil-to-lymphocyte ratio (NLR), lymphocyte-to-monocyte ratio (LMR), and platelet-to-lymphocyte ratio (PLR) are indicators of prognosis in various malignant tumors." (PMID 28489884, 2017). "The inflammatory response to tumor and expression of CRP and SAA in tumor cells may account for the coordinated elevation of SAA and CRP in cancer patients." (PMID 28121629, 2017). "There was a significant positive correlation between the BNP and CRP levels in the cancer patients (r = 0.360, p<0.01), but not in the non-cancer patients." (PMID 28570595, 2017). "The serum CRP levels were also significantly higher in the patients with cancer than in those without (0.99±1.56 vs. 0.18±0.27 mg/dl, p<0.01)." (PMID 28570595, 2017). "Both the plasma BNP and serum CRP levels were significantly higher in cancer patients than those without." (PMID 28570595, 2017). "Specifically, the SIR level of patients with various types of cancer is generally reflected by lymphocyte-to-monocyte ratio (LMR), neutrophil-to-lymphocyte ratio (NLR), platelet-to-lymphocyte ratio (PLR), and C-reactive protein (CRP) levels, which are also called SIR markers." (PMID 29268783, 2017). "Therefore, a series of inflammatory biomarkers, such as c-reactive protein (CRP), neutrophil lymphocyte ratio (NLR) and Glasgow prognostic score (GPS) have been evaluated to predict the prognosis in several cancers." (PMID 29262582, 2017). "Consistent with international consensus for cachexia diagnosis, our results demonstrate systemic inflammation in cancer cachectic vs. non-cachectic patients, with increased circulating CRP, IL6, TNFα, IL8, and IL5 levels." (PMID 28288584, 2017). "The modified Glasgow prognostic score (mGPS) is calculated based on the serum concentrations of C-reactive protein (CRP; cutoff value: 10 mg/l) and albumin (ALB; cutoff value: 35 mg/l) levels, which focusing on systemic inflammation and nutritional status in cancer patients." (PMID 29245945, 2017). "Patients with a high erythrocyte sedimentation rate and normal C-reactive protein mostly have conditions without demonstrable systemic inflammation such as malignancy." (PMID 29138696, 2017). "Sixth, we did not exclude patients with coexisting acute infections or chronic non-malignant inflammatory disorders nor did we adjust the ln (CRP) values for these conditions." (PMID 28286467, 2017). "There was a significant positive correlation between the plasma BNP and serum CRP levels in cancer patients (r = 0.360, P<0.01) but not in those without." (PMID 28570595, 2017). "CRP is a highly sensitive, but nonspecific inflammatory marker that can be expressed by several cancer cells." (PMID 27124056, 2016). "Our results demonstrated that a high serum CRP level was a prognostic factor in IHCC patients with stage I/II cancer (P = 0.006, Kaplan-Meier Method) but not stage III/IV cancer (P = 0.126, Kaplan-Meier Method)." (PMID 27733196, 2016). "As we know, both CRP and PNI are influenced by various non-cancer-related conditions, and the ratio of CRP and PNI could therefore minimise the potential basis." (PMID 27557504, 2016).
cancer (continued). "Therefore, a series of inflammation-based biomarkers, such as C-reactive protein (CRP), neutrophil-to-lymphocyte ratio (NLR), and platelet-count-to-lymphocyte ratio (PLR), have been analysed in various cancers." (PMID 27212808, 2016). "In the present study, there was evidence of mild systemic inflammation in the cancer group, with approximately one third having an elevated circulating C-reactive protein, but not in the healthy elderly." (PMID 27454226, 2016). "Serum levels of C-reactive protein are (CRP) higher in patients with neoplastic conditions and numerous studies have been performed to clarify the etiologic and prognostic role of the high-sensitivity CRP (hs-CRP) in cancer." (PMID 26848624, 2016). "CRP and albumin as acute-phase proteins, which constitute the GPS score, are sensitive and reliable markers that reflect the systemic-inflammatory response in cancer patients." (PMID 27149487, 2016). "The combination of CRP and albumin in the GPS may reflect both the presence of a systemic inflammatory response and progressive nutritional decline in cancer patients." (PMID 26929186, 2016). "Therefore, several inflammation-based hematological biomarkers, such as C-reactive protein (CRP), Glasgow prognostic score (GPS) and prognostic nutritional index (PNI) have been analysed in various cancers." (PMID 27557504, 2016). "Interaction between CRP and leptin is likely to be minimal in the study on cancer mortality, unlike previous evidence suggested in cardiovascular disease." (PMID 26632325, 2016). "Previous reports have indicated that both CRP and PNI are related to cancer prognosis." (PMID 27557504, 2016). "Although serum CRP is an agreed biomarker, cancer cachexia can be present in the absence of overt systemic inflammation." (PMID 27537502, 2016). "Compared with other systemic inflammatory markers, such as C-reactive protein 38 and the Glasgow Prognostic Score, NLR is easily calculated from routine complete blood counts with differentials, which is an essential blood test in cancer patients." (PMID 26632736, 2015). "At present, the complex molecular basis of the relationship between poor clinical outcome in patients with cancer and elevated CRP serum levels is not fully elucidated, and several possible explanations have been postulated." (PMID 26248232, 2015). "In addition, patients with advanced-stage cancers had higher levels of CRP-SAA and total SAA compared with those with early-stage cancers." (PMID 26264146, 2015). "Levels can rise for numerous reasons independent of the cancer; this also reduces the value of single versus serial CRP measurements." (PMID 26717416, 2015). "Regarding measurement of the systemic inflammatory response, the combination of C-reactive protein (CRP) and albumin (ALB) may be useful for diagnosing not only chronic inflammation but also nutritional status in cancer patients." (PMID 25022764, 2014). "CRP is a sensitive but non-specific serum biomarker induced by infectious and non-infectious processes including cancer and tissue damage." (PMID 24800842, 2014). "Older age, male sex and higher CRP were traits more common in DM patients with malignancy than in those without." (PMID 24713868, 2014). "Three articles evaluating CRP levels in PM/DM patients with malignancy and those without were included in the meta-analysis." (PMID 24713868, 2014). "Herein, we have examined the genotypes of three common CRP non-coding SNPs (rs7553007, rs1205, rs3093077) in tumor/normal sample pairs of 5 cancer types (n = 141)." (PMID 25025473, 2014). "We found that PM/DM patients with malignancy had higher serum CRP and ESR levels than the patients without, especially for DM patients, whose ESR level was above 35 mm/h." (PMID 24713868, 2014). "Since the initial work, a decade ago the combination of C-reactive protein and albumin, the Glasgow Prognostic Score (GPS/mGPS), has been shown to have independent prognostic value in more than 60 studies (>30,000 patients with cancer)." (PMID 26316945, 2014).
cancer (continued). "Many clinical findings reveal that CRP tends to increase in cancer patients, but the direct relation has not yet been established." (PMID 24800842, 2014). "The CRP was not significantly different between at cancer diagnosis (mean: 7.77 mg/L, ± S.D.: 13.94) and after-treatment (5.00 mg/L, ± S.D.: 11.52) (paired t-test: p = 0.129)." (PMID 25061977, 2014). "CRP-positive patients had a significantly poorer prognosis than patients whose levels were below the cut-off value (log-rank test, p<0.01; cancer-specific survival rate: CRP-positive, 89.5%; CRP-negative, 66.6%)." (PMID 23833661, 2013). "The two best performing molecules that can distinguish RM from cancer are CA125 (AUC = 0.752) and CRP (AUC = 0.708), while the best molecules which can separate RM and HC are PDGF-AB/BB, PDGF-AA, sIL6R and Leptin (AUC = 0.815, 0.731, 0.739 and 0.73, respectively)." (PMID 24244307, 2013). "Retrospective clinical series on patients in Glasgow, Scotland, for whom data from the Scottish Cancer Registry, including Gleason score, Prostate Specific Antigen (PSA), C-reactive protein (CRP) and albumin, six months prior to or following the diagnosis, were included in this study." (PMID 23768149, 2013). "By contrast, the cancer-specific survival rate of CRP-positive patients was the same as that of CRP-negative patients in those with >13 nodes counted." (PMID 23833661, 2013). "By contrast, cancer-specific survival in CRP-positive patients was the same as that of CRP-negative patients in those with LNR >0.15 or >13 nodes retrieved." (PMID 23833661, 2013). "In this situation, C-reactive protein (CRP) and neutrophil-to-lymphocyte ratio (NLR), indicators of inflammation, have been suggested as surrogate markers for a relationship between inflammation and cancer." (PMID 23409924, 2013). "Despite these strong associations between CRP, SUA, and the risk for diverse types of cancer, CRP is unlikely to be a specifc cause of cancer." (PMID 23369448, 2012). "Likewise, data on predictive ability of CRP and YKL-40 are based on cancers that occurred within the first 5 years after blood sampling." (PMID 22095223, 2012). "There are particularly strong negative correlations between CRP levels and cancer survival in a wide variety of cancer types." (PMID 22963460, 2012). "Early carcinomas were detected with 33% sensitivity for CEA + IL-8 and 28% for CEA + CRP." (PMID 22954206, 2012). "This response appears to be prevalent amongst cancer patients with elevated CRP measured in almost 80% of 106 patients with inoperable nonsmall cell lung cancer (NSCLC), 40% of whom had >5% weight loss." (PMID 21760776, 2011). "The patients were selected on the basis that measurements of C-reactive protein, albumin and calcium had been performed and were therefore not necessarily representative of all cancer patients diagnosed and treated in the North Glasgow area." (PMID 21266974, 2011). "Previously, in large cohort studies, a number of biochemical parameters (other than C-reactive protein and albumin that compose the mGPS) including bilirubin, Alk phos, GGT and calcium, have been reported to predict overall and cancer-specific survival." (PMID 21266974, 2011). "Concerning CRP, we found that neutropenic septic cancer patients showed a significantly higher concentration, 25.9 ± 11.2 mg/dL, in comparison with CRP concentration from non-neutropenic patients, 19.7 ± 11.4 mg/dL (P = 0.009)." (PMID 21595932, 2011). "The strongest associations (Spearman's correlation ⩾0.3) in both the non-cancer and cancer groups were found between albumin, C-reactive protein and Alk phos, AST and ALT, AST and GGT and ALT and GGT (all P<0.001)." (PMID 20717110, 2010). "In these analyses it is still not clear whether the elevation of CRP is a cause or consequence of tumour growth, although one study did take this into account, and demonstrated that the mean time between blood sampling for assay of CRP and development of cancer was 5.8 years, suggesting the former." (PMID 19732183, 2009).
cancer (continued). "In summary, although CRP has been used as a static measurement and levels have been correlated with disease status and survival in cancer and other diseases, close multiple sequential measurements of CRP have essentially not been explored." (PMID 19948067, 2009). "However, if those cases of cancer that were diagnosed within 2 years of sampling (hence cancers that may have been present, but not yet diagnosed) were removed from the analysis, the relationship between elevated CRP levels and increased risk of any cancer no longer existed." (PMID 19732183, 2009). "Similarly, an inflammation-based score, based on two routinely measured acute phase proteins (C-reactive protein and albumin) and the Glasgow Prognostic Score (GPS) has been reported to predict the cancer-specific outcome in Dukes’ B colon cancer." (PMID 19209171, 2009). "The basis of the independent relationship between an elevated C-reactive protein concentration and poor survival in cancer is not clear." (PMID 17024120, 2006). "Cancer patients with an acute phase response (C-reactive protein >10 mg l−1, n=26) had reduced metabolism as measured with the erythromycin breath test 1/TMAX (Kruskal–Wallis Anova, P=0.0062) as compared to controls (C-reactive protein ⩽10 mg l−1, n=14)." (PMID 12177794, 2002). "However, according to our knowledge, this study is the first to assess serum ADAM15 concentrations in CRC patients in comparison to classical tumor markers—carcinoembryonic antigen (CEA) and cancer antigen 19-9 (CA19-9)—and a marker of the inflammatory process, C-reactive protein (CRP)." (PMID 40725774, 2025). "Third, adjustments were made considering the coexistence of autoimmune or inflammatory conditions; however, C-reactive protein was not routinely measured and could not be accounted for; the coexistence of active cancer was also not accounted for." (PMID 39780945, 2025). "In terms of cancer, the expression of KS-containing proteins has been reported in the tumor compartment of high-grade pancreatic cancer as well as astrocytoma; however, how KS tumoral expression in these contexts relates to CRP levels was not defined." (PMID 41614767, 2025). "The most common blood test abnormality in patients with as-yet-undetected cancer was a raised inflammatory marker, with 74–79% of tested patients having at least one abnormal erythrocyte sedimentation rate (ESR) or C-reactive protein (CRP) result pre-diagnosis." (PMID 39799273, 2025). "One might expect SCFA depletion to associate with higher gut inflammation (since SCFAs normally suppress inflammation), but in that study, most patients (cachectic and non-cachectic alike) had elevated CRP due to cancer, possibly masking any difference." (PMID 40572244, 2025). "We also analyzed protein factors released in the supernatants of US-treated cancer cells, detecting well-known tumor markers (e.g., CA19-9, CEA, and CA125), as well as proteins as candidate novel biomarkers for the detection of PC, particularly B2M, CRP, TIMP1, and Galectin-3." (PMID 40563629, 2025). "Blood-based biomarkers of inflammation, such as neutrophil-to-lymphocyte ratio (NLR), C-reactive protein (CRP), platelet-to-lymphocyte ratio (PLR), and lactate dehydrogenase (LDH) are routinely available biomarkers that have been widely investigated in different cancers." (PMID 40165971, 2025). "Among inflammatory markers, CRP (16.2 [5.6–44.0] vs. 1.6 [1.2–4.2] mg/L, p < 0.001), ESR (26.0 [18.0–42.0] vs. 15.0 [10.0–25.0] mm/h, p < 0.001), and fibrinogen (419.0 [350.0–509.0] vs. 329.0 [286.0–398.0] mg/dL, p = 0.003) were all significantly elevated in the cancer group." (PMID 40299527, 2025). "When combining lymphocytes and CRP, several scholars found that lymphocyte to C-reactive protein ratio (LCR) may be a more promising biomarker for reflection of the systemic immune-inflammation status in patients with malignancies." (PMID 41211424, 2025).
cancer (continued). "Furthermore, CRP and the mGPS were not elevated in almost all subjects, supporting the notion that the inflammatory state of cancer patients should be monitored more closely." (PMID 40498221, 2025). "CRP may not be routinely tested for cancer patients receiving ICI therapy at our site; therefore, CRP and mGPS may be less useful as predictors for clinical decision making in this population." (PMID 39817619, 2025). "Notably, the serum level of C-reactive protein (CRP) has served as an indicator of systemic inflammation, which has been correlated with physical and psychological symptoms, physical function, and survival in patients with advanced cancer." (PMID 39765960, 2024). "Furthermore, a relationship between GSDM D, CRP, and CEA could suggest the immune system’s involvement in cancer progression." (PMID 39766111, 2024). "However, CRP is not routinely tested in all new cancer patient at diagnosis, nor routinely repeated during treatments." (PMID 38404120, 2024). "The measurement of CRP and albumin that are present in the GPC showed promise in predicting complications, which is worth discussing the need to include such parameters in the staging and mandatory preoperative surgical preparation in this disease and, possibly, in all malignant neoplasms." (PMID 38985034, 2024). "However, CRP was elevated in various conditions such as malignant carcinoma or infective disease, so using CRP to detect PsA singly was not precise enough." (PMID 39335643, 2024). "This study investigated whether plasma CRP, IL‐6 and YKL‐40 had diagnostic value in 753 patients referred with nonspecific signs and symptoms of cancer to a diagnostic outpatient clinic." (PMID 36440611, 2023). "In particular, to improve the power of the MR analysis, the CRP variance explained by genetic instruments should be discussed in terms of the biological effects of selected SNPs or CRP levels on cancer mortality to compensate for the lack of functional analysis of SNPs." (PMID 36996866, 2023). "If the general cut‐off for CRP (>10 mg/L) was used, the sensitivity was 0.44, specificity was 0.85, the positive predictive value was 0.35 and the negative predictive value was 0.89 for a cancer diagnosis." (PMID 36440611, 2023). "In addition, a positive correlation between FLCs with CRP and CEA may reflect the immune system response during cancer development." (PMID 37176734, 2023). "KMF inhibits NOS and COX-2; it also lowers C-reactive protein (CRP) levels and inhibits pro-inflammatory NFkB, which, in the presence of oxidative stress, upregulates the expression of antioxidant enzymes, which can further lead to cancer progression and chemoresistance." (PMID 37894581, 2023). "We investigated whether CRP, IL‐6 and YKL‐40 had diagnostic and prognostic value in patients referred with nonspecific signs and symptoms of cancer." (PMID 36440611, 2023). "Studies of CRP in cancer populations have not focused on CRT20,21." (PMID 36864082, 2023). "However, the significant limitation in the application of CRP as a biomarker for assessing cancer cachexia is the variability in cutoff values employed in previous research studies and the lack of standardization of recognizable cutoff values of CRP." (PMID 37755304, 2023). "Certain systemic inflammatory markers, such as C-reactive protein (CRP), tumor necrosis factor alpha (TNF-α), interleukin-6 (IL-6), neutrophil-to-lymphocyte ratio (NLR), and platelet-to-lymphocyte ratio, are known to play a prognostic role in various types of cancer following surgery." (PMID 38137474, 2023). "Similarly, comparing CRP levels in the cancer patients subgroup, those with CRP > 100 mg/L showed no response to treatment, suggesting that inflammation is an important driver in addition to the main diagnosis." (PMID 36904164, 2023). "CRP is now considered to have prognostic value in patients with cancer independent of tumor stage." (PMID 36915049, 2023).